NQO1 (NAD(P)H quinone dehydrogenase 1)
Diseases named in the same sentence as NQO1 in open-access papers (continued):
Sharing a sentence is not in itself a finding about the gene and the disease.
cancer (continued). "The underlying mechanism of NQO1 in tumorigenesis remains is still unclear, upregulation of NQO1 is thought to help cancer cells deal with elevated oxidative stress." (PMID 37583897, 2023). "It is important to underline that NQO1 expression is highly activated in cancer cells with mutant Kirsten rat sarcoma viral oncogene homolog (KRAS) signaling." (PMID 37175546, 2023). "An NQO1 deficiency in cancer cells leads to a delay in cell cycle progression at the G2/M phase through reduced c-Fos-mediated CKS1 expression." (PMID 36793872, 2023). "Consistent with clonogenic survival data, a quantitative analysis of γH2AX foci in cancer cells revealed that ionizing radiation increased DSBs in cancer cells deficient for NQO1/c-Fos/CKS1 signaling." (PMID 36793872, 2023). "In the current study, an NQO1 deficiency led to reduced CKS1 expression in cancer cells and delayed cell cycle progression at the G2/M phase." (PMID 36793872, 2023). "Previously, our group reported that NQO1 in cancer cells induces rapid degradation of Aurora-A during mitotic progression, specifically demonstrating that an NQO1 deficiency leads to aneuploidy during mitotic progression in irradiated cancer cells." (PMID 36793872, 2023). "We performed a comprehensive analysis including 43,736 cancer cases and 56,173 controls genotyping of the rs1800566 polymorphism of NQO1 to assess the effect of this functional SNP on cancer susceptibility." (PMID 36338728, 2022). "Among the enriched CCs, The cytoplasm (associated with 6 KGs: OAS1, OAS3, IRF9, HPGD, TP53INP1 and NQO1) has been found to be associated with most proteins that are highly expressed for cancer." (PMID 35617355, 2022). "NQO1 amplifications, mutations, and deletions have been identified in a variety of cancers, and P187S NQO1 in particular has been associated with an increased cancer risk and leads to decreased cellular NQO1 activity and protein concentration." (PMID 35048115, 2022). "Homozygous NQO1 knock-out mice revealed cancer-associated phenotypic traits when exposed to chemical or radiological insults." (PMID 36504709, 2022). "Studies have found that rs1800566 polymorphism of NQO1 is linked to different cancers, but their associations remain controversial." (PMID 36338728, 2022). "Here we describe an extensive analysis of the stability and function of naturally-occurring variants (found in the COSMIC and gnomAD databases) of the cancer-associated human NAD(P)H:quinone oxidoreductase 1 (NQO1)." (PMID 36504709, 2022). "The NQO1 gene rs1800566 polymorphism has been widely discussed in the literature as a related risk factor in cancer." (PMID 36338728, 2022). "Our comprehensive study between cancer susceptibility and NQO1 rs1800566 polymorphism was tried best to conduct convince conclusions based on a larger sample size." (PMID 36338728, 2022). "In another cancer study, the NQO1 rs1800566 polymorphism has been linked with poorer response to drugs of chemotherapy." (PMID 36338728, 2022). "Although two previous meta-analyses (Guo and Ding) has been reported about NQO1 gene rs1800566 polymorphism, they focused on single cancer type, included a small samples, went short of comprehensive subgroups." (PMID 36338728, 2022). "NQO1 is a good target for early cancer diagnosis, prognosis, and therapy due to its association with cancer." (PMID 36144654, 2022). "Nrf2-resistant cancer cells were observed to have higher levels of Nrf2 and other associated genes, such as NQO1, MRP-1, HO-1, CGLM, and CGLC." (PMID 35571115, 2022). "More in-depth studies in the future should be confirmed between NQO1 rs1800566 polymorphism and cancer susceptibility." (PMID 36338728, 2022). "Alterations in NQO1 functionality are associated with a variety of diseases, including cancer, Parkinson's and Alzheimer diseases, diabetes, multiple sclerosis, schizophrenia, metabolic syndrome and benzene toxicity." (PMID 34537677, 2021).
cancer (continued). "With detoxification, NQO1 overexpression is often considered to be correlated with apoptosis in cancer cell, though the underlying mechanism of apoptosis and the overexpression of NQO1 is still controversial." (PMID 34481509, 2021). "In this work, we investigated these relationships using the human NQO1 as a model of multifunctional protein, and evaluated the effect of two mutations, the cancer-associated polymorphism P187S and the phosphomimetic mutation S82D on several functional traits." (PMID 34537677, 2021). "People who have a polymorphism in the NQO1 enzyme are presumed to have increased xenobiotics toxicity and, consequently, a higher risk of developing some cancers." (PMID 34356648, 2021). "People who have a polymorphism in the NQO1 enzyme are presumed to have increased xenobiotic toxicity and, consequently, an increased risk for developing certain cancers." (PMID 34356648, 2021). "Although the activity of NQO1 has been implicated in the development of human cancer, the clinical significance of NQO1 has yet to be elucidated." (PMID 34067204, 2021). "In individuals with polymorphism in the NQO1 enzyme, it has been demonstrated that some allelic variants predispose to developing cancer." (PMID 34356648, 2021). "β-lap was reported to induce cancer cell death via an NQO1-dependent programmed necrotic pathway, which caused robust ROS elevation and PARP1 hyperactivation." (PMID 34676172, 2021). "Changes in the activity of NQO1 are associated to different pathologies, including cancer and cardiovascular and neurodegenerative diseases." (PMID 32825392, 2020). "The NQO1*2 genotype has been linked to a higher risk for several types of cancer and poor survival rate after anthracycline‐based chemotherapy." (PMID 31605637, 2020). "Studies show that NQO1 is upregulated in certain types of cancer and associated with resistance towards anticancer drugs." (PMID 32605023, 2020). "NAD(P)H quinone oxidoreductase 1 (NQO1; DT-diaphorase; EC 1.6.5.2) is a multi-functional and stress-inducible flavoprotein whose activity is associated with different pathologies, particularly with cancer." (PMID 32825392, 2020). "Conversely, cancer cell lines that express inactivating and destabilizing NQO1 polymorphic variants (such as p.P187S and p.R139W) are resistant to certain cancer treatments and are associated with increased cancer risk and poor prognosis." (PMID 32825392, 2020). "In fact, inhibition of PARP1—a critical factor involved in DNA damage response and repair of modified DNA bases and SSBs—prior to treatment with NQO1-bioactivatable drug causes a synergistic cancer cell death." (PMID 32974194, 2020). "The selectivity of this compound for tumors is associated with the fact that cancer cells generally have higher NQO1 compared to normal cells." (PMID 33381269, 2020). "NQO1 upregulation in cancers leads to the development of diagnostic or therapeutic agents based on NQO1 activity." (PMID 32922184, 2020). "Our understanding of the roles of the multifunctional NQO1 protein in many physiological and pathological states, particularly in those associated with oxidative insults such as cancer and neurological disorders, is growing steadily." (PMID 32825392, 2020). "A critical role of protein dynamics in the activity and stability of NQO1 is further supported by the study of the inactivating and destabilizing effects of the cancer-associated p.P187S polymorphism." (PMID 32825392, 2020). "Mutations found in both exome-sequencing initiatives and in cancer cell lines cause mild to catastrophic effects on NQO1 stability and function." (PMID 33153185, 2020). "Polymorphisms of NQO1 (e.g., C609T) are also closely related to a high incidence of various cancers." (PMID 32645959, 2020).
cancer (continued). "Two polymorphic forms of human NQO1 have been associated with increased cancer risk: the NQO1*2 allele (rs1800566) and the NQO1*3 allele (rs1131341)." (PMID 31431515, 2019). "In this regard, deoxynyboquinone (DNQ) and isobutyl–deoxynyboquinone (IB-DNQ) are NQO1 bioactivatable substrates that cause the production of large amounts of ROS that cannot be tolerated by the cancer cells, leading to their death." (PMID 31428936, 2019). "Altogether these data suggest that, beyond the expression of NQO1 itself, the NQO1 polymorphism has a major influence on the sensitivity of cancer cells to some chemotherapeutic drugs." (PMID 31480790, 2019). "The aim of the study was to investigate in such experimental model the role of NQO1 polymorphism on cancer cell sensitivity to quinone-based therapeutic drugs." (PMID 31480790, 2019). "The increased oxidative stress inherent in human cancers has been assumed to underlie the higher expression of NQO1, which at the same time can help to cope with the elevated redox alteration." (PMID 31189950, 2019). "ß-lap acts through an NQO1-dependent mechanism and creates a significant amount of reactive oxygen species (ROS) which will lead to damage to the DNA strands and cause cancer cell death." (PMID 31858276, 2019). "Consistent with this, NQO1 has been extensively explored to achieve highly selective and sensitive detection or visualization of tumor-associated events in different cancers." (PMID 31189950, 2019). "The association between NQO1 expression and drug response was robustly observed across and within individual cancer types." (PMID 30139972, 2018). "Several types of human cancers are developed due to the NQO1 polymorphisms reducing the NQO1 enzymatic activities." (PMID 30595797, 2018). "Although the situation in vivo is likely more complex, these concepts will be particularized and shown to be critical for cancer-associated NADP(H):quinone oxidoreductase 1 (NQO1) (Section 3 and Section 4)." (PMID 30011855, 2018). "A common cancer-associated polymorphism, P187S, decreases protein activity and levels in cancer cells by enhancing NQO1 degradation by the UDP." (PMID 30011855, 2018). "The decreased or null NQO1 activity is due to polymorphisms which reduce or eliminate these benefits and thus contributes to the incidence of cancer." (PMID 30154939, 2018). "Although a lowered or absent NQO1 activity is correlated with increased susceptibility for human cancer development, several studies reveal that NQO1 is upregulated in a number of cancers." (PMID 30595797, 2018). "Previous studies of the association between the NQO1 C609T polymorphism and human cancers other than NPC resulted in mixed findings." (PMID 30160047, 2018). "In this work, we show that the CTD plays key functional and regulatory roles in NQO1, and remarkably, how it is crucial for the manifestation of the multiple deleterious effects of the cancer-associated p.P187S polymorphism." (PMID 28291250, 2017). "Since the full length mRNA of NQO1*3 is still representing one to two-thirds of the whole mRNA, it is unclear if the higher risk for specific cancers can be explained solely by erroneous splicing." (PMID 28236663, 2017). "The two most prevalent variants in the human population are NQO1*2 (NQO1 609C>T; NQO1 P187S; allelic frequency: 0.22–0.47) and NQO1*3 (NQO1 465C>T; NQO1 R139W; allelic frequency: 0.00–0.05), which are connected to a higher risk for specific cancers." (PMID 28236663, 2017). "Overexpression of NQO1 is associated with poor prognosis in human cancers including breast, colon, cervix, lung and pancreas." (PMID 27966538, 2016). "Despite the clear implications of NQO1 expression in the clinicopathological features and prognosis of these cancers, the molecular mechanisms underlying the pro-tumorigenic actions of NQO1 have not been fully elucidated." (PMID 27966538, 2016).
cancer (continued). "The results provided here are critical to understanding NQO1 loss-of-function in cancer patients and for the discovery of new ligands aimed at rescuing NQO1 function by shielding the polymorphic variants from proteasomal degradation." (PMID 26838129, 2016). "Many epidemiological studies have investigated the effect of NQO1 rs1800566 polymorphism on carcinogenesis, and the effect seems diverse in different malignant tumors." (PMID 27304192, 2016). "Elevated levels of the oxidoreductase NQO1 in tumours are associated with poor prognosis but how this contributes to cancer is poorly understood." (PMID 27966538, 2016). "NQO1 is affected by several common SNPs of which the C609T serine-to-proline substitution, known as NQO1*2, shows significant correlation with cancer susceptibility." (PMID 27625902, 2015). "In support of prodrug idea and the potential application of NQO1 status as a biomarker for certain cancers, we examined microarray data from the Oncomine database to further investigate the association between NQO1*2 and human cancer." (PMID 27625902, 2015). "The present study together with our previous work hint to that the anti-cancer effects of NQO1 targeting agents are largely associated with the balance of expression and activity of NQO1 and UGT1A." (PMID 25692465, 2015). "The NQO1 C609T polymorphism has been reported to be associated with an increased risk of various cancers such as renal, lung, esophageal, gastric and head and neck." (PMID 24912939, 2014). "Our results add new evidence that the NQO1 Pro187Ser polymorphism contributes to cancer susceptibility." (PMID 24884893, 2014). "Paradoxically, despite the cellular functions of this “cell protector”, the antioxidant role of NQO1 was suggested by evidence that the disruption of the NQO1 gene or genetic polymorphism increased the risk of chemical-induced toxicity and cancers." (PMID 24499631, 2014). "Despite the strong association between NQO1 expression and cancer, there have been few reports of NQO1 protein expression-based outcomes in tumor patients." (PMID 24499631, 2014). "The results emphasize the importance of NQO1 in the genotoxicity of both carcinogens and demonstrate that the levels of NQO1 protein expression and its enzyme activity in human individuals are key determinants for a cancer risk of 3-NBA and AAI to humans." (PMID 24918288, 2014). "The NQO1 C609T polymorphism has been associated with the risk of various cancers such as renal, lung, esophageal, colorectal, and head and neck." (PMID 23497461, 2013). "Our recent finding has indicated that NQO1 is the main intracellular anti-cancer target of TSA in UGT deficient NSCLC cells." (PMID 24244442, 2013). "Because the NQO1 609C>T polymorphism is functional and potentially to be associated with risk of cancer as shown in this meta-analysis, further larger studies are needed, especially for non-colorectal GI cancers in Caucasians and GI cancers in Asians." (PMID 22272361, 2012). "We summarized the data on the association between the NQO1 609C>T polymorphism and risk of GI cancers and performed subgroup analyses by ethnicity, cancer site, and study quality." (PMID 22272361, 2012). "β-lapachone (β-lap), has been known to cause NQO1-dependnet death in cancer cells and sensitize cancer cells to ionizing radiation (IR)." (PMID 21998736, 2011). "The variable frequency of NQO1 makes some populations more susceptible for getting cancerous disease due to the inability to detoxify the carcinogen by null allele." (PMID 21206700, 2010). "The 2.5-fold increase in NQO1 in the kidneys and forestomach of the mice is of some concern due to the cancer-associated haemolytic–uremic syndrome and gastrointestinal toxicity that occurs in some patients treated with MMC." (PMID 15467770, 2004).
cancer (continued). "Therapeutic strategies aimed at restoring NQO1 activity, particularly in individuals homozygous for the C609T polymorphism, may hold significant potential for cancer prevention and treatment." (PMID 41010895, 2025). "This research that indicates NQO1 expression could act as a companion diagnostic test if considering NAPA-based regimens for cancer therapeutics, including OSA." (PMID 40566602, 2025). "Furthermore, low cell expression of NQO1 can potentially provoke the occurrence of cancer, especially when it is associated with smoking or exposure to benzene." (PMID 40002465, 2025). "The majority of the genes synergistically upregulated by inhibition of both PD-L1 and TGF-β were associated with metabolic pathways (Nqo1, Hmgsc1, Sult1a1, Pla2g7, Ugt1A5, Ugt2B5, Abcb1a), that enhance cancer cell proliferation, invasion, and metastasis (Fig-6D)." (PMID 38516270, 2024). "Besides the generally heightened expression across the human cancer types, hypoxia, another hallmark of malignancies, has an impact on NQO1 content and function." (PMID 39120303, 2024). "Overexpression of NQO1 is linked to various cancer pathways." (PMID 38264080, 2023). "Therefore, HR was increased in irradiated cancer cells deficient for NQO1/c-Fos/CKS1 signaling but decreased in cells where this signaling pathway was activated." (PMID 36793872, 2023). "Notably, a NQO1 deficiency in human cancer cell lines led to suppression of c-Fos-mediated CKS1 expression and cell cycle progression." (PMID 36793872, 2023). "Moreover, after cell cycle synchronization using thymidine and release at the G1/S phase, CDK1 kinase activity in NQO1-deficient cancer cells was concurrently increased, as it was in NQO1-expressing cancer cells, but the decrease was delayed." (PMID 36793872, 2023). "However, the mechanisms underlying the activity of NQO1 in cancer cell proliferation, in particular, cell cycle progression, have yet to be clarified." (PMID 36793872, 2023). "We further focused on the mechanisms underlying the effects of NQO1 on cancer cell cycle progression at the G2/M phase, initially examining whether NQO1 modifies the transcriptome associated with the cell cycle at the G2/M phase." (PMID 36793872, 2023). "To further explore the association of cell types and NQO1 in the microenvironment of specific types of cancer cells for study, we analyzed the NQO1 mRNA expression levels on immune cells in various cancer types using TISCH, 16 single-cell datasets showed relatively higher levels of NQO1 mRNA." (PMID 37583897, 2023). "Moreover, our group previously showed that an NQO1 deficiency leads to aneuploidy in irradiated cancer cells during mitotic progression." (PMID 36793872, 2023). "An NQO1 deficiency in cancer cells caused a delay in cell cycle progression at the G2/M phase." (PMID 36793872, 2023). "Understanding the relationship between NQO1 and the tumor mutation burden and microsatellite instability can provide new insights for the development of individualized cancer treatment, thus improving the efficacy of cancer therapy." (PMID 37583897, 2023). "Furthermore, overexpression of CKS1 in NQO1-deficient cancer cells induced a decrease in CDK1 kinase activity compared to that in cells transfected with pCont." (PMID 36793872, 2023). "In addition, overexpression of c-Fos in NQO1-deficient cancer cells suppressed CDK1 kinase activity, an effect that was enhanced by knockdown of CKS1B." (PMID 36793872, 2023). "The mechanisms underlying NQO1/c-Fos/CKS1-mediated regulation of cell cycle progression in cancer cells were studied using siRNA approaches, overexpression systems, reporter assays, co-immunoprecipitation, pull-down assays, microarray analysis, and CDK1 kinase assays." (PMID 36793872, 2023). "The results in this study suggest that NQO1 may be associated with disease onset and progression in patients with sex-specific cancers." (PMID 37583897, 2023).